EGFR (epidermal growth factor receptor)
Diseases named in the same sentence as EGFR in open-access papers (continued):
Sharing a sentence is not in itself a finding about the gene and the disease.
lung cancer (continued). "Treatment-selected mutations, such as EGFR T790M in non–small-cell lung cancer, KRAS G12V in colorectal cancer, and BRAF V600E/ V600K in melanoma have been detected using ctDNA, thus paving way for personalized treatment options." (PMID 35331236, 2022). "The era of precision medicine for lung cancer commenced with accumulating data demonstrating that Epidermal Growth Factor Receptor (EGFR) mutations were highly predictive of response to EGFR tyrosine kinase inhibitors (TKIs)." (PMID 34921524, 2022). "Smoking during treatment with EGFR tyrosine kinase inhibitors in lung cancer patients was associated with a worse prognosis, whereas smoking was associated with better outcomes in patients treated with checkpoint inhibitors." (PMID 36077654, 2022). "Previous studies have identified that augmentation and mutations of EGFR play a critical role in tumorigenesis, and patients suffering from lung cancer harbouring this mutation or amplification benefited most from EGFR tyrosine kinase inhibitors (TKIs)." (PMID 35592520, 2022). "In the present study, we have analyzed the potential relationship between EGFR gene mutations and clinical characteristics in patients with lung cancer in the coal-producing areas of East Yunnan Province." (PMID 35606799, 2022). "Gefitinib (GF) is a RTKI (receptor tyrosine kinase inhibitor) first-choice drug for EGFR mutated advanced lung cancer." (PMID 35813479, 2022). "Although EGFR Tyrosine Kinase Inhibitors (EGFR‐TKIs) has offered an improved progression‐free survival in lung cancer patients with EGFR mutations, drug resistance invariably occurs." (PMID 35794816, 2022). "Tyrosine kinase inhibitor (TKI) therapy has greatly improved lung cancer survival in patients with epidermal growth factor receptor (EGFR) mutations." (PMID 35163707, 2022). "Mutation of epidermal growth factor receptor (EGFR) gene has emerged as a critical issue in the management of lung cancer." (PMID 35605028, 2022). "In agreement, sarcomatoid differentiation is linked to EMT, which was previously shown to impair anti-EGFR sensitivity in lung cancer." (PMID 36033544, 2022). "In lung cancer, for example, some amino acid mutations in EGFR encoded by the driver EGFR gene have been identified, including Leu858Arg (L858R), Thr790Met (T790M), and a partial amino acid deletion encoded by exon 19 (Ex19Del)." (PMID 35664805, 2022). "This research sought to evaluate the impact of the number of brain metastases in prognosticating non‐small cell lung cancer (NSCLC) patients accounting to the role of epidermal growth factor receptor (EGFR) mutations." (PMID 34766737, 2022). "Several studies have emerged using radiomics as a “virtual biopsy” for EGFR mutation status in lung cancer patients, showing moderate performance in the prediction of EGFR mutation status with AUC values ranging between 0.75 and 0.9595–97." (PMID 36284932, 2022). "Similar to our findings, multiple clinical trials have reported that lung cancer patients harboring activating EGFR mutations show resistance to PD-1 and PD-L1 inhibitor treatments." (PMID 35764641, 2022). "For instance, mutation and expression of epidermal growth factor receptor (EGFR) were used to screen for the subpopulation of lung cancer patients for EGFR inhibitors, while PD-1/PD-L1 for checkpoint inhibitors." (PMID 35740511, 2022). "In lung cancer, especially in the adenocarcinoma subtype, the detection of a mutation in the EGFR gene is extremely important for choosing the first line of treatment." (PMID 36497340, 2022). "In recent years, the third-generation EGFR-TKI osimertinib has made great progress in the treatment of EGFR-mutated lung cancer." (PMID 36712673, 2022). "Gefitinib, erlotinib, and afatinib have been approved for lung cancer treatment as a first-line therapy in those cases with EGFR mutations." (PMID 36471329, 2022).
lung cancer (continued). "Dacomitinib has been approved for the first‐line treatment of non‐small cell lung cancer (NSCLC) carrying classical epidermal growth factor receptor (EGFR) mutations; however, real‐world data on its later‐line application are lacking." (PMID 35023313, 2022). "We queried a database of a distinct UCSF-based cohort to identify patients with EGFR-mutant lung cancer whose tumors harbored co-occurring RBM10 mutations." (PMID 35579943, 2022). "During this period, researchers are also developing a more in-depth understanding of lung cancer with EGFR mutations." (PMID 36172729, 2022). "This is particularly urgent in lung cancer, where mutations in EGFR, ALK, ROS, RET, METex14 skipping, BRAF, and KRAS should be identified before initial treatment." (PMID 35862868, 2022). "The Akt, a downstream ally of EGFR, is frequently expressed in breast and lung cancer; its upregulation is also associated with resistance to EGFR inhibitors, EGFR recycling, and cancer cell survival migration." (PMID 36080307, 2022). "EGFR tyrosine kinase inhibitors (EGFR-TKIs) are breakthrough palliative treatments for advanced lung cancer patients with tumors harboring mutations in the EGFR gene." (PMID 36354696, 2022). "Despite the limitations, to our knowledge, this is the first study of dietary factors and the risk of lung cancer by EGFR +/- and histologic subtypes among Southeast Asians." (PMID 36530673, 2022). "The epidermal growth factor receptor (EGFR) gene mutation is the most frequent driver mutation to strongly promote cancer progression in non‐small cell lung cancer (NSCLC)." (PMID 34904383, 2022). "Activating EGFR mutation can be identified in about 15% of lung cancer cases in White populations and in approximately 50% of Asian cases." (PMID 35605028, 2022). "A retrospective study showed that multiple primary malignant tumors occurred more frequently in patients with lung cancer harboring classic EGFR mutations, particularly those with exon 19 deletions." (PMID 35806042, 2022). "Information about the incidence of hippocampal BM according to the lung cancer stage or EGFR/ALK mutation status can serve as a good guide for the indication for HA-WBRT." (PMID 35619920, 2022). "Preclinical studies have shown that some cytotoxic agents and EGFR-TKIs are synergistically active against EGFR-mutated lung cancer cells." (PMID 36553449, 2022). "Epidermal growth factor receptor tyrosine kinase inhibitors (EGFR-TKIs) combined with cytotoxic chemotherapy are highly effective in the treatment of advanced non–small-cell lung cancer (NSCLC) with EGFR mutations." (PMID 36503478, 2022). "Conversely, in stage 4 patients with EGFR mutations or undetected EGFR, the single lung cancer group showed worse survival than the LCF group." (PMID 36233811, 2022). "TIMP2-deficient lung cancer cells grown in spheroids exhibit enhanced epidermal growth factor receptor (EGFR) signaling." (PMID 36624735, 2022). "EGFR Ex19 del and L858R mutations were detected at baseline time point only in three lung cancer patients." (PMID 35402275, 2022). "Studies have shown that drug-resistant lung cancer cells with two mutations (EGFR-activating mutation/C797S) are sensitive to first- and second-generation EGFR-TKIs." (PMID 35840984, 2022). "An ongoing clinical trial is evaluating safety and activity of the combination of osimertinib + alisertib or sapanisertib (an oral inhibitor of TOR complex 1 and 2) in osimertinib-resistant EGFR-mutated lung cancer (NCT04479306)." (PMID 36387232, 2022). "Strikingly, EGFR short variant (SV) was the top mutually exclusive alteration with ARID1A mutations in lung cancers." (PMID 36117191, 2022). "The term exon 19 deletion (ex19del) is collectively used to refer to more than 20 distinct genomic alterations within exon 19 that comprise the most common EGFR mutation subtype in lung cancer." (PMID 35867821, 2022).
lung cancer (continued). "This study has enormous significance in establishing the potential correlation between routine using NGS for EGFR gene mutation diagnosis and clinical practice in the lung cancer patients." (PMID 35606799, 2022). "In lung cancer, it seems to be associated with the acquisition of resistance to EGFR inhibitors, and in breast cancer, it is involved in the epithelial-to-mesenchymal transition." (PMID 35884475, 2022). "The number of brain metastases was a prognostic factor for lung cancer patients either with EGFR mutations or with wild‐type EGFR, with larger number indicating more unfavorble clinical outcomes." (PMID 34766737, 2022). "Targeted therapeutic drugs such as anaplastic lymphoma kinase (ALK) inhibitors and epidermal growth factor receptor (EGFR) inhibitors have showed a promising performance in clinical trials for treating lung cancer patients with ALK or EGFR mutations." (PMID 35801241, 2022). "The efficacy of ICIs is generally poor for EGFR-mutated lung cancer patients, while EGFR-TKIs are effective." (PMID 35407463, 2022). "Promising results have been observed for aumolertinib against lung cancer EGFR mutational cells, suggesting its specificity and admirable pharmacokinetic properties in mammals." (PMID 35677717, 2022). "Detecting tumor-specific DNA in blood is already common clinical practice in cancer patients with known mutational profiles (e.g. EGFR-mutant lung cancer) and therapy will be adapted according to presence or absence of certain tumor-specific mutations." (PMID 35711922, 2022). "In this context, the primary objective of this work was to analyze the presence of EGFR mutations in cfDNA in plasma of 86 patients with lung cancer undergoing oncological treatment and to study their relationship with the response to treatment with TKIs." (PMID 35884384, 2022). "Taken together, the results suggested that inhibiting PKCδ is an effective way to enhance the efficacy of αPD-1 in EGFR-mutated lung cancer." (PMID 36482371, 2022). "In recent years, targeted drugs, such as gefitinib, for epidermal growth factor receptor (EGFR) mutations in lung cancer have gradually entered the clinic." (PMID 35475399, 2022). "Osimertinib has become the standard of care in the first-line setting for patients with advanced lung cancer and sensitizing EGFR mutations." (PMID 35454838, 2022). "Mutations in the epidermal growth factor receptor (EGFR) gene are among the most common mutations in lung cancer." (PMID 36601482, 2022). "In lung cancer patients, epidermal growth factor receptor (EGFR)-TKI treatment has been considered as a risk factor for HBV reactivation." (PMID 36615034, 2022). "Second, the TME in EGFR mutation‐driven lung cancer is poorly immunogenic, lacks infiltration of anti‐cancer immune effector cells, and shows poor response to anti‐PD‐1/PD‐L1 treatment." (PMID 35861366, 2022). "Recently, the importance of AURK inhibition in enhancing BIM- and PUMA-mediated apoptosis upon EGFR-TKI therapy in EGFR-mutated lung cancer cells has been described." (PMID 35463360, 2022). "This was partly consistent with Lindberg’s study, which demonstrated the relationship between EGFR mutations and heterogeneity and aggressiveness of lung cancer." (PMID 35964032, 2022). "Osimertinib is the standard first‐line treatment for non‐small cell lung cancer (NSCLC) patients with epidermal growth factor receptor (EGFR) mutation." (PMID 34958168, 2022). "In the current literature, EGFR gene mutations and protein overexpression are involved in the development and progression of lung cancer." (PMID 35053080, 2022). "A recent study revealed the impact of EGFR mutations on survival; the clinical stage of lung cancer, order of occurrence of lung cancer, and existence of EGFR mutations were important factors for patient survival." (PMID 36233811, 2022).
lung cancer (continued). "Providers’ confidence was correlated with the availability of in-house genomic testing, more than 10 years of oncology experience, and high volumes of patients with lung cancer in general, and patients with EGFR-mutated and ALK-rearranged lung cancer." (PMID 36193188, 2022). "This study revealed the independent occurrence of EGFR mutations in patients with multifocal lung cancers." (PMID 35740676, 2022). "The discovery of tyrosine kinase inhibitors effectively targeting EGFR mutations in lung cancer patients in 2004 represented the beginning of the precision medicine era for this refractory disease." (PMID 36508072, 2022). "The US Food and Drug Administration (FDA) has approved three generations of small molecule tyrosine kinase inhibitors (TKIs) Gefitinib/Erlotinib/Afatinib/Osimertinib as a first line treatment for lung cancer patients harboring EGFR mutations." (PMID 36344580, 2022). "Of note, non‐small cell lung cancer is often associated with an improved prognosis in patients with positive driver gene mutations, such as epidermal growth factor receptor (EGFR) mutation and EML4‐ALK gene mutation." (PMID 35523730, 2022). "In summary, our study showed that CLEC11A expression is increased in lung cancer cell lines and lung cancer tissues harboring mutated EGFR." (PMID 35267664, 2022). "PKCδ as a common mediator of EGFR-mutated lung cancer induces an immunosuppressive effect on cancer." (PMID 36482371, 2022). "Compared to single sequence, they reported that features extracted from the integration of T1CE and diffusion tensor images improved the capacity to determine the EGFR mutation status of BMs derived from lung cancer." (PMID 35912248, 2022). "This is because, among Asians, EGFR mutation-positive lung cancers are overwhelmingly high in females." (PMID 36581856, 2022). "In this proof-of-concept pilot study, we aim to develop and validate a custom 15-gene ctDNA NGS panel for detecting single nucleotide variants and small indels in lung cancer, with primary focus on EGFR mutation analysis in NSCLC." (PMID 36256645, 2022). "In this study, we developed a deep learning-based model to predict EGFR mutation status in patients with lung cancer using 18F-FDG PET/CT scans and multiple public datasets." (PMID 36300191, 2022). "Among cases with known EGFR status, EGFR mutation (EGFR+) was detected in 1,084 (57.29%) lung cancer cases, and EGFR wildtype (EGFR-) was detected in 808 cases (42.71%)." (PMID 36530673, 2022). "Especially, certain molecular subgroups of cancer, like EGFR-mutated lung cancer, were reported to obtain low efficacy of ICB therapy in clinical." (PMID 36482371, 2022). "Research focused on improving antineoplastic therapies in lung cancer has been based on the genomic and proteomic study of tumors with a known specific genetic basis, such as EGFR and KRAS mutations." (PMID 35565331, 2022). "We collected data on EGFR gene mutations and clinical characteristics of 864 patients with the lung cancer." (PMID 35606799, 2022). "EGFR-mutated lung cancer patients receive targeted therapy with significant efficacy and prolonged survival." (PMID 36101742, 2022). "We showed here that a higher L-score was associated with low sensitivity to EGFR inhibitors in lung cancer cell lines." (PMID 35016696, 2022). "Lung cancer patients harboring hyperactivating EGFR mutations are eligible for treatment with EGFR tyrosine kinase inhibitors (TKI)." (PMID 35840561, 2022). "Another study used Drosophila lung cancer models as an in vivo drug screening system to analyze EGFR-associated TKI pathways via enhancer-suppressor assays." (PMID 36003330, 2022). "In summary, we found that higher vegetable consumption was significantly associated with a decreased risk of EGFR+ lung cancer." (PMID 36530673, 2022).
lung cancer (continued). "Although molecular targeted therapy against mutated driver oncogene such as EGFR or ALK has improved the survival rates of patients with lung cancer, BMs remain an important cause of morbidity and are associated with progressive neurologic deficits." (PMID 35619920, 2022). "It has been regarded as an important biomarker because patients with lung cancer BMs harboring EGFR mutations exhibit a better response to treatment as well as clinical features." (PMID 35406466, 2022). "In contrast to lung cancer, the mutation of EGFR in GBM often takes place in the extracellular domain (ECD) instead of the kinase domain." (PMID 35814475, 2022). "Epidermal growth factor receptor (EGFR) is associated with the progression of a variety of cancers, including breast cancer, lung cancer, cervical cancer, and colorectal cancer." (PMID 34973131, 2022). "We identified that CLEC11A, an extracellular C-type lectin, was over-expressed in lung cancer cell lines harboring mutated EGFR." (PMID 35267664, 2022). "Epidermal growth factor receptor‐tyrosine kinase inhibitors (EGFR‐TKIs) have become the gold standard for EGFR‐mutated non‐small cell lung cancer (NSCLC) treatment." (PMID 34904383, 2022). "Epidermal growth factor receptor tyrosine kinase inhibitors (EGFR-TKIs) are widely used for patients with EGFR-mutated lung cancer." (PMID 35571024, 2022). "Mutations or low expression of EGFR are detrimental to the efficacy of anti-EGFR therapy in lung cancer." (PMID 35740594, 2022). "This study expands our knowledge of the spectrum of EGFR mutations among lung cancer patients in the Indian scenario." (PMID 36613084, 2022). "extracted features from T1CE of 61 patients comprising 210 BMs with a size > 5 mm, and used several machine-learning algorithms to predict the EGFR gene mutation status of primary lung cancer, reaching an accuracy of 86.7% (AUC, 0.868)." (PMID 35912248, 2022). "In lung cancer cells, sub-lethal tyrosine kinase inhibitor (TKI) treatment causes drug resistance in EGFR-mutant lung cancer cells via H3K9me2-mediated reprogramming of BCAA metabolism." (PMID 35011702, 2022). "Among NSCLC subtypes, adenocarcinoma is more prone to BM, and the prognosis and treatment strategy for lung adenocarcinoma patients are different from those of patients with other lung cancer types, especially for patients with EGFR gene mutations." (PMID 35069906, 2022). "Mechanically, lung cancer cells taken from the lungs of smokers contain “drive” EGFR mutations and many other “passenger” mutations." (PMID 35864957, 2022). "When the analysis was stratified by EGFR status, statistically significant positive associations were also found for EGFR+ lung cancer (OR = 2.20, 95% CI = 1.50–3.24) and EGFR- lung cancer (OR = 2.86, 95% CI = 1.84–4.47)." (PMID 36530673, 2022). "Oncogenic activating mutations of EGFR are associated with the development and progression of lung cancer." (PMID 35167433, 2022). "The high proportion of women (60–71%) we observed in all three of our cohorts is concordant with a previous study reporting that 57% of EGFR mutations in lung cancer tumours are found in women in Canada." (PMID 36354696, 2022). "The present case thus supports the use of targeted therapy in patients with advanced lung cancer with rare EGFR mutations." (PMID 36042660, 2022). "Identifying EGFR mutation in lung cancer is crucial for appropriate treatment with EGFR tyrosine kinase inhibitors." (PMID 35774697, 2022). "All patients underwent capture‐based targeted next‐generation sequencing (NGS) with a panel of 68 lung cancer‐related genes and were found with EGFR mutation." (PMID 35023616, 2022). "Orthogonal validation of LiquidHALLMARK EGFR variant calls with a reference AS-PCR method in 355 lung cancer specimens revealed an overall concordance of 93.80% (PPA 95.49%; NPA 92.79%), highlighting the excellent accuracy of the assay." (PMID 35486650, 2022).